TLR5 (toll like receptor 5)
Diseases named in the same sentence as TLR5 in open-access papers (continued):
Sharing a sentence is not in itself a finding about the gene and the disease.
corneal infection (2 papers, 2013 to 2017). A viral or bacterial infectious process affecting the cornea. "During corneal infections, IL-1β, IL-6, IL-8, and TNFα are important in the initiation of inflammatory signals and both TLR2 and TLR5 mediate microbial clearance and cytokine production during S. aureus and PA keratitis." (PMID 28796783, 2017). "We found that neutrophils comprised >90% cells in corneal ulcers, and that there was elevated expression of TLR2, TLR4, TLR5 and TLR9, the NLRP3 and NLRC4 inflammasomes and the ASC adaptor molecule." (PMID 23750216, 2013).
cyst (2 papers, 2019 to 2023). A sac-like closed membranous structure that may be empty or contain fluid or amorphous material. "The permissive FDR interpretation for the TLR5 data indicated associations with cyst incidence and early reproduction disorders with maternal calving ease." (PMID 38254914, 2023). "Conversely, V. vulnificus induced Tlr-5/MyD88/Traf-6-mediated immune response in control tilapia fry while enhanced immunity via increased Tlr-2 and Tlr-5-mediated immune response was observed in response to V. vulnificus infection in transgenic cyst fed group." (PMID 31824449, 2019).
cystitis (2 papers, 2009 to 2017). Inflammation of the urinary bladder. "The fact that the in vitro, murine and clinical study data were all characterised by the reduced production of host defence molecules, including bacterial killing peptides and chemokines, provided a mechanistic explanation to link a TLR5 deficiency to repeated infections of the bladder." (PMID 28887442, 2017).
depression (2 papers, 2021 to 2025). "One of the earliest indications of TLR5 involvement in depression came from a clinical study reporting increased TLR5 expression in the peripheral blood of patients with major depressive disorder, which was normalized after antidepressant treatment." (PMID 40558558, 2025). "However, TLR5 is not only involved in bacterial infection but can also be related with depression." (PMID 34819919, 2021). "Previous works have described how TLR3, TLR4, TLR5, TLR7, TLR8, and TLR9 mRNA expressions in peripheral blood mononuclear cells seem to be increased in patients with depression." (PMID 34819919, 2021).
emphysema (2 papers, 2013 to 2014). "Third, expression by lung CD8+ T cells of TLR 2/1 and TLR5 correlated significantly with quantitative emphysema scores in univariate analysis." (PMID 23374856, 2013). "We have previously shown that CD56+ cells express TLRs and that the percentage of lung NK cells expressing TLR5, TLR6, and TLR2/1 correlated with worsening emphysema as determined by computed tomography quantification." (PMID 25078269, 2014). "The percentage of lung CD8+ T cells expressing TLR5 and TLR2/1 increased with worsening emphysema." (PMID 23374856, 2013). "Similarly, NK cells expressing TLR5, TLR6, and TLR2/1 also correlated with worsening emphysema as determined by CT quantification." (PMID 23374856, 2013).
fibrosis (2 papers, 2018 to 2020). the formation of excess fibrous connective tissue in an organ or tissue in a reparative or reactive process. "Recently, it was shown that TLR5 inhibition ameliorates cardiac fibrosis by modulating inflammation and tissues’ remodeling." (PMID 32508664, 2020). "The expression of TLR2 and TLR5 was enhanced especially in vagal neurons in the bleomycin-induced fibrosis model group compared to the saline-treated control group." (PMID 29518161, 2018). "In conclusion, TLR2 and TLR5 expression is enhanced, especially in vagal neurons, in the bleomycin-induced fibrosis model group when compared to the saline treated control group." (PMID 29518161, 2018). "This study also showed that TLR2 and TLR5 expression in nodose/jugular neurons was significantly increased in the bleomycin-induced fibrosis model group compared to the saline-treated control group." (PMID 29518161, 2018). "In conclusion, this study provides evidence that TLR2 and TLR5 are present in pulmonary sensory neurons and that TLR2 and TLR5 expression is enhanced in vagal neurons in the bleomycin-induced fibrosis model." (PMID 29518161, 2018). "In DRG neurons, 41.2% (7/17) of TRPM8 positive neurons expressed TLR5, 59.1% (13/22) of TRPV1 neurons expressed TLR5 and 44.4% (4/9) of TRPA1 neurons expressed TLR5 in the bleomycin-induced fibrosis model." (PMID 29518161, 2018). "50% (3/6) of TRPM8 positive neurons expressed TLR5, 68.4% (13/19) of TRPV1 neurons expressed TLR5 and 62.5% (5/8) of TRPA1 expressed TLR5 in nodose/jugular ganglion in bleomycin induced fibrosis model." (PMID 29518161, 2018). "Interestingly, this study showed an increase in TLR2 and TLR5 expression in pulmonary nodose/jugular neurons and DRG neurons in both the control group and the bleomycin-induced fibrosis group." (PMID 29518161, 2018).
head and neck squamous cell carcinoma (2 papers, 2022). A squamous cell carcinoma that arises from any of the following anatomic sites: lip and oral cavity, nasal cavity, paranasal sinuses, pharynx, larynx, and salivary glands. "TLR-9, TLR-5, TLR-4, TLR-3, TLR-2 and TLR-1 are linked to some clinical parameters of patients afflicted with head and neck squamous cell carcinoma (HNSCC)." (PMID 36224753, 2022).
Herpes simplex infections (2 papers, 2015 to 2019). "For example, exogenous stimulation of TLR5 and TLR9 has been assessed in mouse models of enteric Salmonella and vaginal Herpes simplex infections, respectively." (PMID 26793623, 2015).
intestinal cancer (2 papers, 2019 to 2024). "The results of this study indicate for the first time that high TLR5 expression may be a marker of better prognosis in patients with GC, especially in stage II disease and in the case of intestinal cancer." (PMID 39451226, 2024).
itch (2 papers, 2024 to 2025). "Mechanical itch can be mediated by activating Toll-like receptor 5 (TLR5)-positive Aβ low-threshold mechanoreceptors (Aβ-LTMRs), which convey light touch stimuli and are implicated in alloknesis." (PMID 40558516, 2025). "Gentle touch applied to the skin can simultaneously activate both the neural circuitry involved in transmitting mechanical itch (e.g., TLR5+ LTMRs to Ucn3+/Tac2+ INs) and an inhibitory neural circuitry that effectively suppresses mechanical itch." (PMID 39602426, 2024).
keratitis (2 papers, 2017 to 2020). A corneal disease that is characterized by inflammation of the cornea. "The host-cytokine response towards P. aeruginosa keratitis is mainly induced by LPS stimulation of TLR4/MD-2 and flagellin binding to TLR5." (PMID 33208864, 2020).
lung fibrosis (2 papers, 2018 to 2024). "TLR5 was also detected in 55.7% (34/61) and 42.3% (33/78) of pulmonary nodose/jugular neurons and DRG neurons, respectively, in the bleomycin-induced pulmonary fibrosis model." (PMID 29518161, 2018).
mantle cell lymphoma (2 papers, 2014 to 2017). Mantle cell lymphoma is a rare form of malignant non-Hodgkin lymphoma affecting B lymphocytes in the lymph nodes in a region called the ``mantle zone''. "In mantle cell lymphoma (MCL), TLR1, TLR4, TLR7, TLR9 and TLR10 exhibit significant mRNA levels, whereas TLR2, TLR3, TLR5 and TLR8 are negative." (PMID 25112836, 2014).
myeloid leukemia (2 papers, 2018 to 2022). A clonal proliferation of myeloid cells and their precursors in the bone marrow, peripheral blood, and spleen. "In summary, our results show for the first time that Hsp90 inhibitors suppress TLR5 surface expression and subsequently inhibit NF-κB activation in human myeloid leukemia THP-1 cells." (PMID 29651431, 2018). "The purpose of this study was to investigate the possible modulatory effects of Hsp90 inhibitors on TLR5 expression and NF-κB activation in human myeloid leukemia THP-1 cells." (PMID 29651431, 2018). "In the present study, we investigated the possible modulatory effects of Hsp90 inhibitors on TLR5 expression and signaling in the human myeloid leukemia cell line THP-1." (PMID 29651431, 2018).
myocardial infarction (2 papers, 2024 to 2025). Gross necrosis of the myocardium, as a result of interruption of the blood supply to the area, as in coronary thrombosis. "For example, TLR5 can recognize several pathogen-associated molecules, releasing profibrotic factors and inflammatory cytokines, possibly resulting in myocardial infarction." (PMID 40005451, 2025). "One of TLR family is TLR5 which recognizes several pathogen-associated molecules leading to release of different inflammatory mediators and pro-fibrotic factors causing myocardial infarction." (PMID 38223670, 2024).
parasitemia (2 papers, 2017 to 2021). "In addition, a negative correlation was observed between mRNA expression of TLR4, TLR5, IL-6, and parasitemia levels." (PMID 34336720, 2021). "We also observed a negative correlation between TLR4, TLR5, TRIF, IL-6, IL-10, and IL-12p35 mRNA expression and parasitemia peak levels in infected mice." (PMID 34336720, 2021).
pneumococcal pneumonia (2 papers, 2021 to 2024). A febrile disease caused by STREPTOCOCCUS PNEUMONIAE. "Previous studies demonstrated that i.n. administration of the TLR5 agonist flagellin, either by itself or during antibiotic-treated pneumococcal pneumonia, exerts immunostimulatory effects in the lung." (PMID 39295863, 2024). "We have previously shown that protection against pneumococcal pneumonia can also be induced by prior S. pneumoniae sub lethal infection or therapeutic treatment with a TLR5 agonist." (PMID 33981296, 2021).
pouchitis (2 papers, 2011 to 2024). Acute inflammation in the intestinal mucosa of the continent ileal reservoir (or pouch) in patients who have undergone ileostomy and restorative proctocolectomy (proctocolectomy, restorative). "In addition, our results also show that TLR5 up-regulation is related to inflammation as seen in colectomized UC patients who developed pouchitis." (PMID 22185629, 2011). "The expression of Toll-like receptors (TLRs) is also altered, with a decreased expression of TLR3 and increased expression of TLR5 in normal ileal pouch, and an upregulation of TLR2 expression in pouchitis and upregulation of TLR4 in both normal pouch and pouchitis." (PMID 38929596, 2024).
Pseudomonas infection (2 papers, 2017 to 2021). Infections with bacteria of the genus pseudomonas. "PumA ensures efficient inhibition of innate immune responses by interacting with MyD88 and TIRAP, key adaptor proteins for IL‐1R and the main relevant TLRs in Pseudomonas infection (TLR4 and TLR5), as well as UBAP1 which regulates cytokine receptor pathways." (PMID 28483816, 2017).
renal fibrosis (2 papers, 2022). A final common manifestation of a wide variety of chronic kidney diseases characterized by glomerulosclerosis and tubulointerstitial fibrosis. "SQYSF significantly reduced the degree of renal fibrosis in CKD mice, and remarkably down-regulated the expressions of toll-like receptor 5 (TLR5), nuclear factor-kappaB (NF-κb), p65, tumor necrosis factor (TNF)-α, interleukin (IL)-1β and IL-6." (PMID 35184655, 2022).
Rotavirus infection (2 papers, 2015 to 2018). Infection with any of the rotaviruses. "Rotavirus infection was prevented and cured via the signaling pathway mediated by TLR5 and NOD-like receptor C4 (NLRC4), which led to production of IL-22 and IL-18 (mimicking the Th17-polarization)." (PMID 26213635, 2015).
Sciatica (2 papers, 2021). Pain in the lower back and hip radiating in the distribution of the sciatic nerve. "Consistent with the microarray data, the expression levels of the key genes (TLR4, MMP9, MPO, CAMP, RETN and TLR5) were significantly increased in patients with sciatica compared with healthy controls." (PMID 33535986, 2021). "Network analysis identified TLR4, MMP9, MPO, CAMP, RETN and TLR5 as key genes contributing to the dysregulation of genes in the peripheral blood of patients with sciatica." (PMID 33535986, 2021). "The PPI network suggested that TLR4, MMP9, MPO, CAMP, RETN, TLR5, and IL1RN were key genes in the dysregulation of genes in the peripheral blood of patients with sciatica." (PMID 33573686, 2021). "Bioinformatic analysis revealed that most of the DEGs-baseline were related to immunity and the inflammatory response and that TLR4, MMP9, MPO, CAMP, RETN, TLR5, and IL1RN were key genes involved in the dysregulation of genes in the peripheral blood of patients with sciatica." (PMID 33573686, 2021). "We also found that TLR5, IL1RN, and SLC8A1 were upregulated in sciatica patients at baseline compared with healthy controls and downregulated after integrated TCM treatment compared with baseline, indicating that these genes played an important role in the pathogenesis and remission of sciatica." (PMID 33573686, 2021).
squamous cell carcinoma (2 papers, 2019 to 2023). A carcinoma arising from squamous epithelial cells. "The tumours with strong TLR2nucl or TLR5 expression were mostly virus-negative or HPV-positive keratinizing squamous cell carcinomas, and the patients with these tumours were significantly older than those with mild or negative TLR2nucl/TLR5 expression." (PMID 31238894, 2019).
systemic inflammatory response syndrome (2 papers, 2019 to 2025). SIRS is a serious condition related to systemic inflammation, organ dysfunction, and organ failure. "Conversely, it is well known that TLR-5 recognizes flagellin, which is a component of motile bacteria, and this mechanism has been studied as a biomarker predicting Systemic Inflammatory Response Syndrome (SIRS)." (PMID 40076895, 2025). "Clinical data have shown that the expression of TLR5 on monocytes predicted systemic inflammatory response syndrome (SIRS)." (PMID 30944018, 2019).
toxoplasmosis (2 papers, 2017 to 2020). A parasitic disease contracted by the ingestion or fetal transmission of toxoplasma gondii. "Furthermore, these results suggest that activation of TLR4 and TLR5 could be useful for development of vaccines that elicit T cells to prevent toxoplasmosis in humans." (PMID 29263879, 2017). "We demonstrate protection of HLA-A*11:01, HLA-A*02:01, and HLA-B*07:02 mice against toxoplasmosis by (i) this novel chimeric polypeptide, containing epitopes that elicit CD8+ T cells, CD4+ T helper cells, and IgG2b antibodies, and (ii) adjuvant activation of innate immune TLR4 and TLR5 pathways." (PMID 33046728, 2020).
tuberculosis (2 papers, 2013 to 2022). A chronic, recurrent infection caused by the bacterium Mycobacterium tuberculosis. "A meta-analysis performed with 16 microarray datasets to profile the host transcriptional response in active tuberculosis led to the identification of five upregulated genes: AIM2, BATF2, FCGR1B, HP, and TLR5." (PMID 35456421, 2022). "Both TLR5 and NLRC4 were upregulated in melioidosis (P = 5.4 × 10–13 and 4.2 × 10–10, respectively), but both were upregulated in tuberculosis also (P = 8.1 × 10–10 and 2.4 × 10–11)." (PMID 23383015, 2013). "No alternative ligand has yet been described for TLR5, so it is more difficult to explain why tuberculosis should apparently induce a flagellin-response." (PMID 23383015, 2013). "In support of this hypothesis, the TLRs are upregulated as a group in both melioidosis (TLR1, TLR2, TLR4, TLR5, TLR6, TLR8 and TLR10) and tuberculosis (TLR2, TLR4, TLR5, TLR6, TLR7, TLR8)." (PMID 23383015, 2013).
type 2 diabetes (2 papers, 2017 to 2025). "Mechanistically, bacterial flagellin induces a proinflammatory response by activating Toll-like receptor-5 (TLR5) in macrophages, and the presence of flagellin antibodies in pancreatic biopsies of individuals with type 2 diabetes lends support to this mechanism in humans." (PMID 40768044, 2025).
abscess (1 paper, 2025). An inflammatory process characterized by the accumulation of pus within a newly formed tissue cavity which is the result of a bacterial, fungal, or parasitic infection or the presence of a foreign body. "For instance, TLR5/Rag1 double knockout (DKO) mice demonstrate severe immune dysregulation compared to their TLR5 knockout (T5-KO) and Rag1 knockout (Rag1-KO) littermates, with frequent lethal infections caused by Pasteurellaceae and increased abscess formation in multiple organs." (PMID 40444793, 2025).
airway hyperresponsiveness (1 paper, 2020). "TLR5-deficient mice had approx. 30–50% decreased cytokine expression in local and systemic LPS models of lung inflammation, while airway hyperresponsiveness after ozone or hyaluronan exposure was significantly reduced, and inflammatory gene induction after hyaluronan exposure was abolished." (PMID 31989925, 2020).
allergic asthma (1 paper, 2018). A asthma with a basis in a pathological type I hypersensitivity reaction. "It was recently reported that flagellin and TLR5-activation in the airways can promote allergic asthma by priming allergic sensitization to allergens." (PMID 29518161, 2018).
Atrophy (1 paper, 2024). Any weakening or degeneration, especially through lack of use. "Genetic variants associated with decreased levels of pathogenic proteins ITGB6 (rs8099840), TLR5 (rs1403631, rs75118229), F7 (rs6046), HERC5 (rs406936) and MGA (rs704) were associated with preserved brain volumes over time, including in regions susceptible to infection-specific atrophy." (PMID 39143319, 2024).
avian influenza (1 paper, 2025). Infection of domestic and wild fowl and other birds with influenza A virus. "This may be due to the presence of flagellin-like structures or the inclusion of TLR5 agonists, such as flagellin used as an adjuvant, which can enhance the immune response to avian influenza vaccines and potentially reduce viral replication." (PMID 41331407, 2025).
Barrett esophagus (1 paper, 2022). Esophageal lesion lined with columnar metaplastic epithelium which is flat or villiform.
Bartonella infections (1 paper, 2025). "Previous studies have revealed that specific sites on TLR1, TLR2, and TLR5 genes were significantly associated with the risk of Bartonella infection." (PMID 40678527, 2025). "In this study, we analyzed the polymorphisms in six cell surface TLR genes (TLR1, TLR2, TLR4, TLR5, TLR6, and TLR10) in striped hamsters, aiming to determine their association with Bartonella infections and ectoparasite parasitism, including fleas and gamasid mites." (PMID 40678527, 2025).
brain tumor (1 paper, 2020). "Besides injecting mice intrathecally with flagellin as a proof-of-concept demonstration for a role of activated TLR5 in neuronal injury, we herein tested the impact of TLR5 signaling in the setting of glioblastoma, the most aggressive brain tumor in adults." (PMID 32912327, 2020).
Cachexia (1 paper, 2018). Severe weight loss, wasting of muscle, loss of appetite, and general debility related to a chronic disease. "The increase in LIF production resulting from activation of the TLR5 signaling pathway may contribute to the cachexia-inducing ability of 85As2 cells." (PMID 30410674, 2018). "TLR5 stimulation promoted LIF production, suggesting that this mechanism contributes to activation of the cachexia-inducing ability of 85As2 cells." (PMID 30410674, 2018). "LIF concentration in the plasma was increased by activation of the TLR5 signaling pathway; this suggests that LIF production contributes at least partially to activating the cachexia-inducing ability of 85As2 cells." (PMID 30410674, 2018).
cardiac hypertrophy (1 paper, 2023). "TLR5 triggers inflammatory responses and promotes cardiac hypertrophy, and the deficiency of TLR5 in mice attenuates the cardiac hypertrophy and dysfunction induced by pressure overload." (PMID 37113698, 2023).